DCLK1 (doublecortin like kinase 1)
Diseases named in the same sentence as DCLK1 in open-access papers (continued):
Sharing a sentence is not in itself a finding about the gene and the disease.
cancer (continued). "Though it was the first meta-analysis to assess the diagnostic and prognostic role of DCLK1 in cancer, there were still several limitations in our study." (PMID 29246000, 2017). "Down-regulation of DCLK1 results in loss of cancer-stem-cells (CSCs), and inhibits spheroidal/xenograft growths from hCRC-cells." (PMID 26447334, 2015). "DCLK1 has been identified as a cancer stem cell marker in gastrointestinal, pancreatic, and colorectal cancers, and its overexpression has been associated with tumor progression and poor clinical outcomes in several cancer types." (PMID 38334648, 2024). "DCLK1 is associated with CSCs and promotes characteristics linked with aggressive cancer." (PMID 38003596, 2023). "In cancer, potential mutations in the autoinhibitory domain of DCLK1 might increase its kinase activity." (PMID 37443105, 2023). "There are four isoforms of DCLK1 associated with different cancers." (PMID 37762326, 2023). "In addition, choice of inhibitors and sources, associated with clinical, and cancer cell resistance are limiting factors in creating DCLK1 inhibitors." (PMID 36250024, 2022). "This evidence strongly implies that DCLK1 promotes the aggressive phenotype of cancer; however, the underlying molecular mechanism remains unclear." (PMID 35910805, 2022). "Moreover, cancer-related mutations within the kinase domain were found to adversely affect the kinase activity and/or the structural integrity of DCLK1." (PMID 34445192, 2021). "Importantly, we found that most of the human-cancer derived mutations located within the kinase domain would likely adversely impact DCLK1’s kinase domain structural integrity and/or lead to a reduction of its kinase activity." (PMID 34545159, 2021). "Furthermore, overexpression of DCLK1 is clinically associated with tumor progression and poor prognosis in several human cancers, including HNSCC." (PMID 34336664, 2021). "Dysregulation of DCLK1 in humans and mice is associated with activated pathological cancer stages." (PMID 34069906, 2021). "Here, we hypothesized that IR-induced ataxia telangiectasia mutated (ATM) activation following direct interaction with DCLK1 may lead to the repair of damaged DNA, and increase the survival of cancer cells." (PMID 34268251, 2021). "Since our cohort was comprised of patients with different histologic subtypes of HNSCC, we evaluated the association between DCLK1 expression and clinical outcome in patients with oral (n = 86), oropharyngeal (n=65), laryngeal (n=56), and hypopharyngeal (n=15) carcinoma." (PMID 34336664, 2021). "Microtubule-associated doublecortin-like kinase 1 (DCLK1) is an accepted marker of tuft cells (TCs) and several kinds of cancer stem cells (CSCs), and emerging evidence suggests that DCLK1-positive TCs participate in the initiation and formation of inflammation-associated cancer." (PMID 33348546, 2020). "Loss of the anti-cancer miR-200c leads to an upregulation of DCLK1 and increased cellular motility." (PMID 32756469, 2020). "In addition, it has been demonstrated that DCLK1 is associated with malignant biological behavior and poor prognosis of cancer." (PMID 29246000, 2017). "In summary, our study indicated that DCLK1 could be a risk factor for development of malignant tumors and may serve as a promising diagnostic and prognostic biomarker for malignant tumors." (PMID 29246000, 2017). "Moreover, the observed loss of adhesion is also interesting in light of DCLK1′s roles in neurite formation and elongation and should be investigated further in other cancers known to express DCLK1." (PMID 25605241, 2015). "Indeed, we also speculate that the induced expression of DCLK1.2 splice variants in multiple cancer subtypes is likely to be indicative of a survival and drug-resistance role that could be targetable with new types of small molecule." (PMID 37034755, 2023). "Moreover, targeting DCLK1-specific interacting molecules could help obviate the root cause of cancer metastasis and progression." (PMID 36250024, 2022).
cancer (continued). "In addition, DCLK1 was potential to be a promising diagnostic and prognostic biomarker for malignant tumors, and might serve as an attractive therapeutic target in the treatment of malignant tumors." (PMID 29246000, 2017). "Additionally, we assessed the diagnostic accuracy of DCLK1 in malignant tumors." (PMID 29246000, 2017). "Increased TNF-α levels disrupt the intestinal immune barrier while also promoting stem cell formation of Dclk1+ tuft cells, which serve as cancer cell lineages." (PMID 41515203, 2025). "Beyond transcriptional activation, alternative splicing (AS) events, including alternative promoters (AP) and exon skipping (ES), also play essential roles in determining the diversity and abundance of DCLK1 transcripts in cancer." (PMID 40775208, 2025). "Given the well-known function of DCLK1 in provoking EMT in cancer, we examined the role of DCLK1-L in EMT in ccRCC." (PMID 40775208, 2025). "This review explains how DCLK1 both aids healing and risks promoting cancer by influencing key protective and inflammatory pathways." (PMID 40563698, 2025). "Given the reported variability in expression and function of DCLK1 long and short isoforms across different cancer types, we further explored the dominant oncogenic isoform in ccRCC." (PMID 40775208, 2025). "Despite consistent transcriptional activation, DCLK1 promoter selection and activation can vary across different cancer types." (PMID 40775208, 2025). "This epithelial-to-mesenchymal transition (EMT) phenotype aligns with previous studies that have underscored the role of DCLK1 in promoting EMT in various cancers." (PMID 40839695, 2025). "Emerging evidence identifies the epithelial kinase doublecortin-like kinase 1 (DCLK1)—highly expressed in GI tuft cells and cancer stem-like cells—as a master regulator of post-IR responses." (PMID 40563698, 2025). "We are exploring ways to measure DCLK1 levels as a marker of radiation damage and to design therapies that block its harmful effects—boosting gut recovery while reducing the chance of new cancers." (PMID 40563698, 2025). "A DCLK1 homing peptide was proposed to act as a selective affinity binding navigator and function as a blocker/neutralizer to interrupt the pro-cancer activities of DCLK1." (PMID 40869256, 2025). "Multiple binding partners interacting with distinct motifs in the C-terminal domain likely contribute to DCLK1’s roles in both inflammation and cancer." (PMID 40162222, 2025). "In 2019, researchers found that DCLK1 promoted cell migratory and invasive abilities, typical of cancer metastasis." (PMID 40869256, 2025). "Initially, DCLK1 was reported to play an essential role in neurogenesis and neuronal migration, and was subsequently identified as a cancer stem cell (CSC) marker in gastrointestinal cancers." (PMID 40775208, 2025). "DCLK1, an emerging cancer stem cell marker, is activated during tumorigenesis, triggering cancer stemness and metastasis." (PMID 40775208, 2025). "The mammalian homolog of ZYG-8, DCLK1 (doublecortin-like kinase 1), is upregulated in multiple cancers and there are ongoing efforts to generate inhibitors targeting its kinase activity as a therapeutic strategy." (PMID 39226307, 2024). "Considering DCLK1 played key roles in tumour growth, EMT, tumour immunity, and drug resistance, targeting DCLK1 is a potential strategy for treating cancers." (PMID 38062554, 2024). "Given DCLK1’s involvement in inflammation-related cancer initiation and development, we investigated its role as a potential biomarker and therapeutic target in the progression from normal hepatocytes to HCC." (PMID 38928187, 2024). "For instance, miR-144 directly targets DCLK1, leading to the downregulation of DCLK1 expression, thereby inhibiting cancer cell growth and invasion." (PMID 38928187, 2024).
cancer (continued). "On the other hand, during CRC development, the oncogene Dclk1 is upregulated, promoting the proliferation of cancer stem cells, increasing tumor growth, and reducing sensitivity to conventional therapies." (PMID 38674816, 2024). "DCLK1 is regulated by various miRNAs, which can modulate its expression and, consequently, its role in cellular processes such as tumorigenesis and cancer progression." (PMID 38928187, 2024). "DCLK1 is regarded as a marker of various cancer stem cells and it regulates pro-survival signalling and self-renewal of tumour cells." (PMID 38062554, 2024). "More importantly, these DCLK1+ cells remain quiescent and long-lived for a long time, even in the presence of APC loss, but become potent cancer-initiating cells upon the induction of inflammation." (PMID 38892399, 2024). "These two subtypes of DCLK1 play different physiological and pathological functions in different cancers." (PMID 38980538, 2024). "Prior studies have highlighted DCLK1's impact in propelling the epithelial-mesenchymal transition (EMT) across a spectrum of malignancies." (PMID 38980538, 2024). "In a Dclk1-CreERT2 knock-in mouse model, DCLK1+ cells were short-lived and rarely functioned as intestinal stem cells under physiological and pathological conditions, but they did function as cancer stem cells in tumors formed in ApcMin/+ mice." (PMID 38892399, 2024). "The stem cell marker DCLK1 (doublecortin-like kinase 1) has also been recently identified as a promising kinase involved in cancer stemness, EMT, metastasis, and immune regulation." (PMID 37488598, 2023). "Various drugs are being developed to inhibit DCLK1 expression or activity in cancer patients, aiming to inhibit tumor growth and cancer cell migration." (PMID 37762326, 2023). "The cancer stem biomarker doublecortin-like kinase 1(DCLK1) is included in the top 50 genes positively correlated with GATA3 in HGSOC patients." (PMID 37039909, 2023). "The reduction of DCLK1 has been shown to inhibit cancer stemness and reduce the regenerative capacity of pancreatic cells." (PMID 37996782, 2023). "In cancer stem cells, DCLK1 promotes angiogenesis in a hypoxic environment, since the expression of this protein is upregulated by low oxygen supply, while reducing DCLK1 negatively influences angiogenesis." (PMID 37108193, 2023). "The combinational therapy was found to target cancer stem cells, as suggested by the reduction of cancer stemness factors, such as DCLK-1, CD24, Lgr5, CD29, and CD44, and the colonosphere formation." (PMID 36765950, 2023). "Accordingly, treatment with a selective small molecule DCLK1 kinase inhibitor (DCLK1-IN-1) inhibits DCLK1-dependent cell growth, migration and stemness in cancer cells." (PMID 36979969, 2023). "Foregoing reports have demonstrated a direct functional role for DCLK1 in promoting cancer cell migration and invasion of gastrointestinal (GI) cancers." (PMID 36979969, 2023). "This is an important finding, since the mammalian homolog of ZYG-8 (DCLK1/doublecortin-like kinase 1) is upregulated in a wide range of cancers, and knockdown studies have suggested that it is required for tumor progression." (PMID 38045228, 2023). "Later studies showed that DCLK1 is a novel specific surface marker of tumor stem cells and it shows an increase in several human malignant tumors." (PMID 37443105, 2023). "Doublecortin-like kinase 1 (DCLK1) is a novel biomarker of cancer stem cells and regulates tumorigenesis and EMT." (PMID 38023167, 2023). "A common thread throughout those reports is that elevated expression of DCLK1 promotes pluripotency of cancer stem cells and epithelial-to-mesenchymal transition (EMT) in a kinase-dependent manner." (PMID 36979969, 2023). "In this study, we constructed a series of cancer mutants whose mutations occurred in the AID and its binding site of DCLK1, and provided detailed molecular mechanisms for these cancer mutations through molecular dynamic simulations." (PMID 37762326, 2023).
cancer (continued). "Encouragingly, recent research that zeroes in on the distinct C-terminus of some DCLK1 isoforms has shown potential in countering cancer traits." (PMID 38003596, 2023). "Although there is a plethora of information on neuro-regenerative and cancer-promoting impacts of DCLK1, few research has been conducted on the involvement of DCLK1 in the onset of non-malignant illnesses." (PMID 37443105, 2023). "DCLK1 has been shown to elongate microtubules for cell growth, but excessive elongation can increase cancer cell development." (PMID 37996782, 2023). "Our results showed that patients with high WNT5A levels and low DCLK1 levels in their cancer tissue (Group 1) had a somewhat better prognosis than those grouped based only on low DCLK1 expression." (PMID 37998393, 2023). "Increased levels of DCLK1 in various human cancers including renal, pancreatic, colorectal, and liver have been correlated with cellular activities such as epithelial‐to‐mesenchymal transition, and cell proliferation and migration." (PMID 36896602, 2023). "We discover that doublecortin‐like kinase 1 (DCLK1), a cancer stem cell maker, is correlated with 5‐fluorouracil resistance, and functionally promotes cancer stemness and 5‐fluorouracil resistance in CRC." (PMID 35522902, 2022). "In conclusion, the findings of the current comprehensive systematic review and meta-analysis represent the notable roles of DCLK1 CSC markers in cancer progression and predicting poor clinical outcomes of CRC patients." (PMID 35717205, 2022). "Most importantly, a series of studies have suggested the role of DCLK1 as a potential cancer stem cells (CSCs) marker in several tumours." (PMID 35522902, 2022). "Five studies comprising 785 cases evaluated the prognostic role of DCLK1 on cancer progression or recurrence." (PMID 35717205, 2022). "To confirm the versatility of our findings across various cancer cells, we performed additional analyses and found that the DCLK1/XRCC5/COX2 axis is conserved in many types of solid cancer cell lines including breast, lung and pancreatic cell lines." (PMID 35910805, 2022). "Cancer-related processes including cancer progression, cancer therapy resistance, and metastasis are regulated by DCLK1-expressing CSCs." (PMID 36250024, 2022). "Since commercial antibodies target the C-terminal domain of DCLK1, the unique oncogenic functions of DCLK1 isoforms, as well as their possible contribution to tumor growth in cancer tissues like CRC, need to be investigated further." (PMID 35717205, 2022). "Several studies have discussed the inhibition of tumor cell proliferation along with neoplastic cell arrest when the DCLK1 gene, which is expressed in both cancer and normal cells, was targeted successfully." (PMID 36250024, 2022). "Previous research has revealed that DCLK1 regulates p65 as a prosurvival signaling that is essential for cancer formation and progression." (PMID 36369000, 2022). "Doublecortin-like kinase 1 (DCLK1), a protein molecule, has been identified as a tumor stem cell marker in the cancer cells of gastrointestinal, pancreas, and human colon." (PMID 36250024, 2022). "Mounting evidences suggested that DCLK1, a CSCs marker, was functionally involved in maintaining cancer stemness." (PMID 35522902, 2022). "To elucidate the involved mechanism of DCLK1‐mediated cancer stemness and 5‐fluorouracil resistance in CRC, we performed mass spectrometry (MS) to identify DCLK1‐binding proteins in cells." (PMID 35522902, 2022). "In the current study, we discover that DCLK1 is correlated with 5‐fluorouracil resistance, and functionally promoted cancer stemness and 5‐fluorouracil resistance in CRC." (PMID 35522902, 2022). "The overexpression of DCLK1 protein is in various cancers, including gastric, pancreatic, colon, renal, and breast." (PMID 36250024, 2022). "Collectively, these data suggested that DCLK1 promoted 5‐fluorouracil resistance by β‐catenin signalling‐mediated cancer stemness." (PMID 35522902, 2022).